CD163 (CD163 molecule)
Diseases named in the same sentence as CD163 in open-access papers (continued):
Sharing a sentence is not in itself a finding about the gene and the disease.
hematoma (16 papers, 2018 to 2025). A hematoma is a collection of blood from a vascular structure into an extravascular space. "Acute serum-soluble CD163 (sCD163) levels are significantly associated with the expansion of hematoma volume and peri-hematomal edema." (PMID 31717522, 2019). "The current findings provide direct evidence that Tregs enhance post-ICH hematoma clearance by increasing CD163 expression levels in the brain." (PMID 40585999, 2025). "In contrast, during the chronic recovery phase, “anti‐inflammatory” (M2‐type) microglia aid in hematoma resolution and tissue repair by phagocytosing cellular debris and engaging in receptor‐mediated clearance via CD163, CD36, and CD47." (PMID 40994248, 2025). "Through HCAR2-dependent regulation of the CD36/CD163/HO-1 axis, niacin enhances M2 microglial phagocytosis, accelerates hematoma clearance, reduces hydrocephalus, and improves neurological outcomes while mitigating neuroinflammation and oxidative stress." (PMID 41205412, 2025). "CD163, a hemoglobin scavenger receptor and M2 microglial polarization marker, plays a crucial role in hematoma resolution." (PMID 40585999, 2025). "It was shown that patients with higher concentrations of soluble CD163 presented increased hematoma absorption and improved neurological deficits." (PMID 39451197, 2024). "In in vivo and in vitro ICH models, fractalkine located in neuronal cells can interact with the unique fractalkine receptor CX3CR1 and promote hematoma absorption through the PPAR-γ/CD163/HO-1 signaling pathway." (PMID 36970539, 2023). "It was found that CD163 expression is increased in both hematoma and perihematomal regions within 6 h after ICH." (PMID 37955765, 2023). "It has also been pointed out that the PPAR-γ agonist monascin increases the levels of haptoglobin (Hp) and CD163 on the surface of phagocytes in plasma, accelerating hematoma absorption through the Hp–Hb–CD163 pathway." (PMID 36970539, 2023). "In the present study, we demonstrate that CDNF enhances expression of the scavenger receptors, CD36 and CD163 on activated microglia/macrophages at the hematoma accumulation stage." (PMID 36792604, 2023). "We found that the CR3 agonist LA-1 prominently promoted CD163/HO-1 expression and reduced residual hematoma volume after ICH." (PMID 36189326, 2022). "CR3 activation exacerbated ICH-induced brain injury, as well as enhanced CD163/HO-1 expression and promoted hematoma clearance." (PMID 36189326, 2022). "CR3 agonist LA-1 aggravated neurological dysfunction, neuronal cell death, and oxidative stress response on day 7 after ICH, as well as enhancing the expression of the CD163/HO-1 pathway and accelerating hematoma resolution." (PMID 36189326, 2022). "CCL17 therapy promotes early hematoma regression after intracerebral hemorrhage through the CCR4/ERK/Nrf2/CD163 pathway." (PMID 35959472, 2022). "We found less CD163-HO-1 expression and bigger hematoma volume in minocycline treatment as compared to the ICH control group." (PMID 36189326, 2022). "CR3 activation upregulated CD163/HO-1 expression and promoted hematoma resolution, and these items were also measured in this part of the experiment." (PMID 36189326, 2022). "IL-19 activation of ERK and its downstream protein Nrf2 play a pivotal role in the expression of CD163 and its enhancement of hematoma clearance after GMH." (PMID 33532035, 2021). "Scavenger receptor CD163, a class B glycoprotein, has been shown to induce microglia/macrophage phagocytosis which induced hematoma clearance." (PMID 33532035, 2021). "IL-20R1 CRISPR-knockdown plasmid ameliorated the therapeutic effects of rIL-19 on hematoma clearance, which effected the expression of CD163 and Nrf2." (PMID 33532035, 2021). "PPAR-γ promotes hematoma clearance and plays a protective role through the Hp-Hb-CD163 pathway in a rat collagenase infusion ICH model." (PMID 30123388, 2018).
hematoma (continued). "We observed the effects of PPAR-γ on the brain water content, hemoglobin levels, and the expressions of CD163 and Hp in Western blot and real-ime PCR; meanwhile, we measured hematoma volumes and edema areas by MRI scanning." (PMID 30123388, 2018). "In conclusion, PPAR-γ promotes hematoma clearance and plays a protective role possibly through the Hp-Hb-CD163 pathway in a rat collagenase-induced ICH model." (PMID 30123388, 2018). "We and others have demonstrated that CD163 is expressed and contributes to hematoma clearance following ICH, but the functions of CD163 have not been investigated after SAH." (PMID 29867324, 2018). "Additionally, niacin facilitates the recruitment of M2-type microglia to the periventricular region, where they promote hematoma clearance via the CD36/CD163/HO-1 axis, reducing iron deposition and oxidative stress." (PMID 41205412, 2025). "The scavenging effect of CD163 on “free” Hb is known to play a vital role in hematoma absorption in patients with intracerebral hemorrhage (ICH), where spontaneous, non-traumatic bleeding leads to hemoglobin release with damaging potential to the surrounding tissues." (PMID 39451197, 2024). "It was further identified that CD163 was responsible for the improved hematoma resolution effect by CCL17, which included activation of the C-C chemokine receptor 4 (CCR4) with downstream ERK and Nrf2 activation, improving the outcome of intracerebral hemorrhage in a relevant animal model." (PMID 39451197, 2024). "The Hp-CD163-HO-1 is the major pathway of microglia-mediated hematoma clearance." (PMID 36189326, 2022). "The recombinant CCL17 (rCCL17) administration might promote hematoma resolution by increasing the expression of CD163 on microglia/macrophages, further reducing perihematomal edema and improving neurobehavior outcomes." (PMID 36704330, 2022). "It has been reported that treatment with CCL17, a specific ligand of CCR4, promotes hematoma resolution through the CCR4/ERK/Nrf2/CD163 pathway, thereby, improving neurological function, which is associated with microglia-mediated erythrocyte phagocytosis and clearance of tissue debris." (PMID 35959472, 2022). "Meanwhile, LA-1 upregulated CD163/HO-1 expression and reduced residual hematoma volume after ICH." (PMID 36189326, 2022). "Current literatures suggest that ERK1/2 may increase the expression of nuclear factor erythroid 2-related factor 2 (Nrf2), which has been shown to enhance hematoma resolution by increasing CD163 in microglia/macrophages." (PMID 33532035, 2021). "Haptoglobin-Hb-CD163 as well as hemopexin-heme-LRP1 (low-density lipoprotein receptor-related protein-1) is believed to be the most important endogenous scavenging pathway which participates in hematoma/blood component resolution following ICH." (PMID 30123388, 2018). "We hypothesize that PPAR-γ will promote hematoma clearance via CD163 and Hp upregulation, therefore reducing brain edema and improving BBB integrity after ICH." (PMID 30123388, 2018). "In addition, increased Hb levels have been found to upregulate neuronal CD163 expression, although a significant association between neuronal CD163 and endogenous hematoma absorption was not confirmed in the current investigation." (PMID 36970539, 2023). "Furthermore, patients with naturally high levels of macrophage/microglial CD163 may have faster rates of hematoma resorption, and/or less neuroinflammation due to rapid sequestration of toxic hemoglobin." (PMID 31717522, 2019). "Adoptive transfer experiments further confirmed that Tregs promoted hematoma resolution by upregulating efferocytosis-related receptors (MERTK and AXL), ligands (Gas6 and C1q), and the hemoglobin scavenger receptor CD163." (PMID 40585999, 2025). "The expression of CD36 and CD163 scavenger receptors on microglia/macrophages can be simultaneously increased through the PPAR-γ signaling pathway, effectively promoting endogenous hematoma absorption." (PMID 36970539, 2023).
hematoma (continued). "Third, Nrf2 helps upregulate CD163 and CD36 expression in microglia; thus, we cannot exclude the possibility that the protective effect of albumin in promoting hematoma clearance is due to the contributions of other Nrf2 signaling pathways." (PMID 33708336, 2021). "Although the duration of exogenous CDNF in blood circulation is relatively short, it still could increase the expression of CD163 and CD36 in the peri-hematoma area, implying that CDNF in the circulation could induce peripheral monocytes/macrophages to remove hematoma at the early stage of ICH." (PMID 36792604, 2023).
Hepatitis (16 papers, 2013 to 2026). Inflammation of the liver. "Increased levels of CD163 on the surface of macrophages in the liver have been observed in patients with hepatitis, and this is associated with increased levels of the shed form of sCD163 in serum [21, 23, –25]." (PMID 30370392, 2018). "This was accompanied by high levels of soluble CD163 in sera from patients with CPI-induced hepatitis, which has been shown to be a biomarker of monocyte/macrophage activation in other acute liver injury syndromes." (PMID 35454819, 2022). "Parallel to these systemic changes, liver biopsies from CPI-induced hepatitis patients show focal immune aggregates composed of cytotoxic granzyme B+CD8+ T cells co-localising with CD163+ and CCR2+ expressing MoMFs." (PMID 35454819, 2022). "The level of IL-4, IL-17 and CD163 was positively correlated with the grade of hepatitis activity; marked grades of hepatitis activity showed almost the highest degree of expression, and vice versa." (PMID 33906302, 2021). "Immunohistochemical analysis of hepatic monocytes confirmed that CD163 was significantly increased in the liver tissue of patients with hepatitis." (PMID 24597777, 2014). "However, animals develop hepatitis with hepatic accumulation of macrophages with M2 phenotype expressing CD163, MerTK, and TGF-β." (PMID 35639478, 2022). "However, little is currently known of the regulatory mechanisms that influence the expression of CD163 on monocytes in liver tissues of hepatitis patients." (PMID 24597777, 2014). "Additionally, both pro-inflammatory and anti-inflammatory genes, such as Cd163, Ho-1, Il-1β, Il-10, and Ccl5, along with CD163 and HO-1 protein expression, were markedly suppressed, supporting the notion of alleviated liver inflammation." (PMID 41522337, 2026). "In CPI-induced hepatitis, circulating classical monocytes were expanded and showed an activated, tissue homing phenotype (CD163highCCR2highCCR7low), in which the proportion of classical monocytes and CD163 expression correlated positively with disease severity." (PMID 35454819, 2022). "Plasma sCD163 and peritumoral CD163+ cell infiltration was more likely a maker of active hepatitis rather than a marker of tumor progression." (PMID 23555776, 2013).
meningioma (16 papers, 2016 to 2025). A generally slow growing tumor attached to the dura mater. "For example, a high degree of macrophage infiltration (CD68 + macrophages and CD68 + CD163 + M2 macrophages) has been associated with tumour aggressiveness and therapy resistance of meningiomas." (PMID 38102708, 2023). "Moreover, CD163 is implicated in the pathogenesis of various cancers, including chronic lymphocytic leukemia, multiple myeloma, meningioma, Hodgkin’s lymphoma, and colorectal cancer." (PMID 40681545, 2025). "This genotyping method and four-colour flow cytometry has enabled us to assess the variability in the largest immune cell infiltrate population, M2 macrophages (CD45+HLA-DR+CD14+CD163+) in 42 meningioma samples, and to suggest that underlying genetics is relevant." (PMID 32070062, 2020). "The results showed that the expression of the M2 phenotype‐related genes MRC1 and CD163 was markedly higher in grade II meningioma." (PMID 36994665, 2023). "The numbers of CD4 and CD163+ cells tended to be higher in recurrent meningiomas than in primary meningiomas (P = 0.057 and 0.084, respectively)." (PMID 33330078, 2020). "Our study also revealed that the numbers of CD4+ lymphocytes and CD163+ macrophages tended to be higher in recurrent meningiomas than in primary tumors." (PMID 33330078, 2020). "Elevated peripheral NLR was not correlated with the number of intratumoral neutrophils or CD8, CD4, or CD163+ cells in meningioma." (PMID 33330078, 2020). "Researchers found that 48.5% and 71.4% of grade I and II meningioma, respectively, were positive for CD163." (PMID 33042832, 2020). "Next, we analysed 42 meningioma samples for both M2 macrophages (CD45+HLA-DR+CD14+CD163+) and tumour cells (CD45−HLA−DR−CD14−CD44+) at Passage 0, and related these results to mutational status." (PMID 32070062, 2020). "In multiple areas within the malignant meningioma specimen, a network of interconnected CD163+ cells (SI." (PMID 27834402, 2016). "In a benign meningioma specimen, antigen retrieval followed by immunohistochemistry for CD163 and Imaris rendering, revealed CD163+ multinucleated tubular structures surrounding clusters of meningioma cells (SI." (PMID 27834402, 2016). "One study assessed the expression of CD163 in 50 samples of meningioma." (PMID 33042832, 2020). "Further immunohistochemistry analysis comparing AKT1 E17K mutants to WHO grade I NF2-negative samples showed significantly lower levels of CD163-positive activated M2 macrophages in meningiomas with mutated AKT1 E17K, signifying a more immunosuppressive tumour microenvironment in NF2 meningiomas." (PMID 32070062, 2020). "Similarly, others have reported an increased PD-L1 and CD163 expression in higher grade meningiomas, thus suggesting a role for immune avoidance in higher grade tumors associated with worse prognosis." (PMID 31039818, 2019). "To identify the infiltration and functional characteristics of macrophages in meningiomas and adjacent normal meningeal tissue, we performed IHC staining and analyzed the expression of CD68, CD163, and CD206." (PMID 35637794, 2022). "Patient-derived meningioma spheroids closely recapitulated morphological and molecular features of matched patient tissues, including patient histology, genomic alterations, and components of the immune microenvironment, such as a CD68 + and CD163 + positive macrophage cell population." (PMID 38102708, 2023). "Interestingly, CD163 and CD206 are ubiquitously expressed in these infiltrating macrophages, especially in high-grade meningiomas, suggesting that they may be induced to become TAMs with an M2 phenotype in the TME." (PMID 35637794, 2022). "The histiocytes were positive for CD68, CD163, and ALK, and negative for EMA, PR, and SSTR2, which ruled out the diagnosis of meningioma." (PMID 36915094, 2023).
meningioma (continued). "CD163 is a well-established M2 macrophage marker and has previously been shown using immunohistochemistry to be in high abundance in atypical grade II meningiomas but, unlike previous authors, we correlated CD68 and CD163 expression with NF2 status." (PMID 32070062, 2020).
asthma (15 papers, 2013 to 2025). "Multivariable regression found the COPD phenotype associated with greater age and pack-years smoking; the asthma phenotype with younger age, female gender, smoking history, and lower adiponectin levels; and greater WA% with greater BMI, younger age, higher soluble CD163, and higher CD4 counts." (PMID 27488495, 2016). "In asthma patients, the interaction between HDAC8 / Gal3 increases the CD163 expression; therefore, given the role of CD163 in M2 differentiation, and the role of M2 cells in Th2 differentiation, CD163 in asthma can be considered as a target for the targeted therapy route." (PMID 37422662, 2023). "It was reported that this intermediate CD14+CD16+ subset (same subset is also referred to as CD14++CD16+ or CD14highCD16+) was expanded in patients with allergies and asthma and expressed a number of M2 surface markers such as CD163, CX3CR1, IL-4R, TGF-β1 and IL-10." (PMID 24358127, 2013). "Conversely, lung MΦ in the bronchoalveolar lavage of patients with asthma, a disease generally associated with a M2 MΦ phenotype, expressed less CD163 than the MΦ from healthy non-asthmatics." (PMID 24205083, 2013). "Recently, increased surface expression of CD163 and CD206 on AMs was identified in association with exacerbation of SEA, suggesting that these macrophages may also have an anti-inflammatory role that like humans, is associated with the severity of asthma." (PMID 36920969, 2023). "The expression levels of HLA-DR proteins on blood CD14+CD163+ M2a monocytes were significantly elevated in the COPD-only group (7695 ± 3743 MFI) compared to the HS group (5391 ± 3153 MFI, adjusted p = 0.026) and the asthma group (4716 ± 1679 MFI, adjusted p = 0.012)." (PMID 41462706, 2025). "Although increased AM expression of CD163 and CD206 has been associated with an anti-inflammatory phenotype in conjunction with severe, but non-neutrophilic, asthma in humans, it is uncertain whether the same is true of equine AMs in the context SEA." (PMID 36920969, 2023).